MED15 (mediator complex subunit 15)
Diseases named in the same sentence as MED15 in open-access papers (continued):
Sharing a sentence is not in itself a finding about the gene and the disease.
tumor (continued). "Whether MED15 plays a role in lipid accumulation, tumor cell proliferation, and cell viability in ccRCC and its possible regulatory mechanism remain unclear." (PMID 38649345, 2024). "MED15 depletion reduced lipid accumulation and inhibited tumor progression in ccRCC." (PMID 38649345, 2024). "Our results showed that MED15 promotes lipid accumulation and tumor progression in ccRCC." (PMID 38649345, 2024). "Increased TGF-β1 and reduced CD16, CD57, and MED15 expressions in the tumor might independently favor the prognosis." (PMID 32439976, 2020). "Tumoral upregulation of CD16, CD57, and MED15 were associated with increased risk of mortality, while overexpression of TGF-β1 might improve prognosis." (PMID 32439976, 2020). "MED15, a general transcriptional cofactor of the mediator complex involved in RNA polymerase II dependent transcription, was found to be edited in introns in all three tumor samples." (PMID 32308773, 2020). "Considering the strong overexpression of MED15 in TGCT and EC as presented here, the involvement of the MED15-SREBP-FASN axis in tumor formation and differentiation should be investigated in detail with the aim to potentially develop diagnostic biomarker and identify novel therapeutic targets." (PMID 26377566, 2015). "Interestingly, pre-eminently the pluripotent spermatogonia exhibit moderate MED15 expression in the tumor-free testis." (PMID 26377566, 2015). "Likewise, samples of NSGCT, YST and CC exhibited elevated nuclear and cytoplasmic MED15 expression as compared to tumor-free testes and SEM." (PMID 26377566, 2015). "In conclusion, MED15 is differentially expressed in tumor-free testis and TGCT." (PMID 26377566, 2015). "Interestingly, MED15 was found to be homogeneously expressed in NSGCT (positive index >0.8) pointing at a possible role for MED15 in selection of precursor tumor cells during carcinogenesis." (PMID 26377566, 2015). "Interestingly, NSGCT showed an elevated MED15 positive index indicating a homogeneous expression in the tumor, whereas tumor-free testes and SEM showed significantly lower positive indexes (p < 0.001)." (PMID 26377566, 2015). "In addition, MED15 knockdown reduced lipid accumulation and suppressed tumor growth in vivo." (PMID 38649345, 2024). "As such, PCQAP/MED15 may have an important role as a tumour-suppressor gene." (PMID 27663357, 2016). "In clear cell renal cell carcinoma (ccRCC), SREBP2 interacts with MED15 that acts as a SREBP2 coactivator to promote cholesterol biosynthesis enzyme expression, resulting in enhancing malignant tumor behavior phenotypes." (PMID 40308757, 2025). "HIF-2α activates MED15, which acts with SREBP1 and SREBP2 to further enhance lipid dependency in tumor cells." (PMID 41451091, 2025). "Med15, a member of the mediator complex, was remarkably upregulated in HCC and correlated with tumour stage, histological grade and unfavourable clinical outcomes." (PMID 38493218, 2024). "Here, MED15 was demonstrated to be a dominant factor for HIF-2α-dependent lipid accumulation and tumor progression." (PMID 38649345, 2024). "SEM weakly express the Mediator complex subunit MED15, whereas NSGCT and especially EC show significantly enhanced expression compared to tumor-free testis." (PMID 26377566, 2015). "In this study, we found MED15 nuclear and cytoplasmic expression to be significantly higher in NSGCT as compared to tumor-free testes and SEM." (PMID 26377566, 2015). "While MED15 is absent or low in tumor-free testis and SEM, NSGCT highly express MED15, hinting at the diagnostic potential of this marker to distinguish between SEM and NSGCT." (PMID 26377566, 2015). "In tumor-free seminiferous tubules, MED15 protein expression was absent or only low expressed in spermatogonia." (PMID 26377566, 2015).
tumor (continued). "Regarding molecular rearrangements, among the neoplasms with available data, the SFPQ/PSF::TFE3 fusion was the most frequent genetic alteration found (14 cases, 74%), followed by ASPL/ASPSCR1::TFE3 (3 cases, 16%), RBM10::TFE3 (1 case, 5%), and MED15:TFE3 (1 case, 5%)." (PMID 39410016, 2024). "Older ages, greater stages, relative tumoral upregulation of CD16, CD57, and MED15, as well as downregulation of TGF-β1 (compared to the expressions in the adjacent normal tissue), poorer histologic grades, and increases in tumor volume might predict a higher rate of mortality." (PMID 32439976, 2020). "In tumor-free testes the MED15 protein expression was absent or low." (PMID 26377566, 2015).
cancer (12 papers, 2014 to 2025). A tumor composed of atypical neoplastic, often pleomorphic cells that invade other tissues. "MED15 deficiency in colorectal (HCT116) and renal (786-O) cancer cell lines resulted in a significant decrease in colony formation." (PMID 39947475, 2025). "We analyzed data from TCGA and identified a positive correlation between MED15 and HIF1α mRNA levels across various cancers." (PMID 39947475, 2025). "Further mechanistic studies revealed that MED15 facilitated the binding of HIF1 to HREs in the chromatin of hypoxic cancer cells." (PMID 39947475, 2025). "Collectively, these data indicate that MED15 plays a critical role in promoting cancer cell proliferation in vitro." (PMID 39947475, 2025). "Data from TCGA and GTEx revealed that the expression of Med15 was increased in many cancer tissues, including HCC tissues, compared with that in normal tissues." (PMID 38493218, 2024). "Med15, a member of the mediator complex, is participates in tumorigenesis and contributes to the diagnosis, prognosis and treatment of many cancers." (PMID 38493218, 2024). "MED15 is overexpressed in several cancer types, including BC among others, and correlates with the clinical outcome and the recurrence of the disease." (PMID 35205279, 2022). "MED15 is overexpressed in different cancers and correlates with the clinical outcome and the recurrence of the disease." (PMID 33772081, 2021). "Whether MED15 is involved in lipid homeostasis in human diseases, including cancers, remains unknown." (PMID 38649345, 2024). "Our studies showed that therapeutic strategies including MED15 depletion or blockade of the binding of MED15 to SREBPs might provide alternative treatment options for these drug-resistant cancers." (PMID 38649345, 2024). "However, the molecular mechanism by which MED15 overexpression contributes to those malign diseases remains unknown yet, although it is assumed that they are the result from an increased and sustained transcriptional activation." (PMID 35205279, 2022). "Consequently, MED15 may serve as a prognostic marker as well as a potential therapeutic target in cancer." (PMID 33772081, 2021). "This is the case of Mediator complex subunit 15 (MED15), which is overexpressed in a wide range of human cancers." (PMID 34428113, 2021).
bacterial infection (1 paper, 2014). "Here we find that a conserved transcriptional regulator MDT-15/MED15 links xenobiotic detoxification and immune responses in a manner that is important for protection during bacterial infection." (PMID 24875643, 2014). "To determine whether MDT-15/MED15 is also involved in the regulation of these genes during bacterial infection, we infected C. elegans with P. aeruginosa PA14 for 8 hours and used qRT-PCR to compare the induction levels of several immune response genes in mdt-15(RNAi) and control animals." (PMID 24875643, 2014).
neurological diseases (1 paper, 2024). "Recent studies have implicated GLS, RAI1, GIPC1, MED15, EP400, MEF2A, and CNKSR2 in neurological diseases, with GLS, GIPC1, MED15, RAI1, and MEF2A sharing the same repeat loci reported in this study." (PMID 38871700, 2024).
MED15 also shares sentences with these, for which no sentence is quoted: breast carcinoma (4 papers); bladder cancer (2); hepatocellular carcinoma (2); Ataxia (1); atherosclerosis (1); autism (1); bipolar disorder (1); cardiomyopathy (1); cardiovascular diseases (1); chorionic carcinomas (1); colon cancer (1); embryonic carcinomas (1); germ cell tumor (1); heart malformations (1); Intellectual disability (1); lipid metabolism disorders (1); lung carcinoma (1); neuroblastoma (1); neurodegenerative disease (1); pharyngeal cancer (1); teratoma (1); testicular germ cell tumours (1); urothelial bladder cancer (1); yolk sac tumor (1).